ENSG00000267228 (novel transcript)
Gene: Protein-coding gene on chromosome 18 (47,108,188 to 47,176,345, reverse strand). Ensembl gene ENSG00000267228.
Genetic constraint (gnomAD): Missense variants: 79 observed, 77.89 expected, observed/expected ratio (o/e) 1.01, 90% interval 0.85 to 1.22. Synonymous variants: 36 observed, 31.57 expected, observed/expected ratio (o/e) 1.14, 90% interval 0.87 to 1.51.